LMO7DN (LMO7 downstream neighbor)
Synonyms: C13orf45; C13orf45-IT1; TCONS_00021569; LMO7DN-IT1
Gene: Long non-coding RNA gene on chromosome 13 (75,870,573 to 75,883,811, forward strand). Ensembl gene ENSG00000178734.
Diseases named in the same sentence as LMO7DN in open-access papers:
LMO7DN is named in the same sentence as 1 disease in open-access papers, as found by Europe PMC text mining. Sharing a sentence is not in itself a finding about the gene and the disease. The quoted sentences say what the papers report.
lung adenocarcinoma (1 paper, 2022). A carcinoma that arises from the lung and is characterized by the presence of malignant glandular epithelial cells. "LMO7DN has also been suggested as a predictor of lung adenocarcinoma associated with ferroptosis." (PMID 35785155, 2022).